EGFR (epidermal growth factor receptor)
Diseases named in the same sentence as EGFR in open-access papers (continued):
Sharing a sentence is not in itself a finding about the gene and the disease.
breast carcinoma (continued). "In particular, it has been suggested that elevated expression of EGFR may serve as an indication of anti-estrogen resistance in ER α positive breast cancer cells." (PMID 32435229, 2020). "Recent studies have also suggested that SERPINE1 plays an important role in breast and pancreatic cancer, and that the overexpression of SERPINE1 could induce activation of the EGFR signaling pathway in breast cancer cells." (PMID 33680908, 2020). "However, while a small population of recurrent breast cancers do respond to erlotinib, this and other EGFR inhibitors have had low overall success in clinical trials of advanced disease." (PMID 32552913, 2020). "EGFR over-expression has been linked to metastatic phenotypes and metastatic breast cancers are considered resistant to EGFR inhibitors, which have not been clinically effective at reducing metastasis or overall survival in breast cancer patients." (PMID 31597954, 2020). "Furthermore, it would be of interest to investigate predictive value of these biomarkers in populations that include breast cancer patients receiving EGFR-co-targeted treatments." (PMID 33024132, 2020). "Furthermore, EGFR inhibition leads to a reduction of the number and the area that breast cancer cells invade both in MDA-MB-231 (ca. 80%) and shERβ MDA-MB-231 cells (ca. 55%)." (PMID 33050027, 2020). "EGFR is positive in 75% of cases of basal-like breast carcinoma." (PMID 33218360, 2020). "TNBC is a subtype of breast cancer characterized by a deficiency of expression of progesterone, estrogen, and epidermal growth factor receptor, and the most aggressive cancer among other breast cancer subtypes due to the lack of therapeutic target." (PMID 33126606, 2020). "EV EGFR levels significantly correlated with tumour EGFR levels, tumour size and Ki67 tumour expression, suggesting that this microfluidic electrochemical immunosensor for EV EGFR may be useful in early diagnosis of breast cancer patients." (PMID 33143170, 2020). "We determined whether inhibition of FAK function affects EGFR dimerization in the breast carcinoma cells." (PMID 33050232, 2020). "In addition, cytokeratin 5 can be applied for the identification of triple-negative breast cancers, which contains the group of epithelial EGFR (epithelial growth factor receptor) overexpressing basal-like breast cancers." (PMID 32466213, 2020). "However, to the best of our knowledge, there are no reports showing the participation of TNFα or NF-κB in resistance to EGFR TKIs in breast cancer." (PMID 32391269, 2020). "Furthermore, our PM were previously used to efficiently conjugate Cetuximab, showing an effective active targeting against the epidermal growth factor receptor (EGFR) in overexpressing breast cancer cells." (PMID 32098204, 2020). "Furthermore, it would be of interest to investigate the predictive value of EGFR and EGFR ligands, which is undetermined in breast cancer." (PMID 33024132, 2020). "Thus, further studies investigating EGFR and EGFR ligands in large distinct subgroups of breast cancer patients are recommended." (PMID 33024132, 2020). "The study revealed that triterpenoids from Liquidambaris Fructus might exert anti-breast cancer effect by directly inhibit multiple protein targets and signaling pathways, especially ErbB4 and EGFR and related pathways." (PMID 33246450, 2020). "Taken together, these findings suggest that GREM1 may act as a ligand for EGFR, thereby stimulating the proliferation and growth of breast cancer cells." (PMID 32572171, 2020). "Knockdown or pharmacological inhibition of ANO1 in ZR75-1 and HCC1954 breast cancer cell lines resulted in a decreased phosphorylation of EGFR at Y992 as well as of phosphorylation of downstream signaling molecules - ERK1/2, AKT and calmodulin kinase II (CaMKII) under normal growth conditions." (PMID 33250781, 2020).
breast carcinoma (continued). "This suggests that differential expression of AnxA6 may be useful for the prediction of not only the survival, but also the likelihood of basal-like breast cancer patients to respond to EGFR-targeted therapies." (PMID 32784650, 2020). "Indeed, it has been reported that the estrogen receptor beta-1 (ERβ1) induces the degradation of EGFR by enhancing the EGFR-Cbl interaction in basal-like breast cancer cells." (PMID 33114139, 2020). "SGCE loss increases degradation of epidermal growth factor receptor (EGFR) through enhanced interaction between EGFR and its ubiquitination ligase c‐Cbl, providing a potential mechanism for understanding the failure of EGFR‐targeted treatment in breast cancer." (PMID 32714745, 2020). "Indeed, a novel role of cannabinoid receptor 2 in inhibiting EGF/EGFR pathway in breast cancer has recently been reported." (PMID 32547536, 2020). "These trials were also designed with the assumption that breast cancers were EGFR dependent and without consideration of EGFR-associated adaptive response mechanisms." (PMID 33256808, 2020). "Moreover, ranks 1 and 2 (gefitinib and afatinib) represented two EGFR inhibitors, additional proof of the importance of this receptor in breast cancer treatment." (PMID 32532074, 2020). "Moreover, EGFR signaling appears to exert different roles in breast cancer cells during invasion of primary tumors, dissemination and metastasis." (PMID 32350443, 2020). "These patients included two metastatic NSCLC patients with EGFR mutations who received erlotinib or afatinib, a NSCLC patient with an EZR/ROS1 fusion who was treated with crizotinib and a HER2 positive metastatic breast cancer patient with FGFR amplification who received everolimus." (PMID 33192972, 2020). "Additionally, the authors examined the use of multiple SERS tags for ER, EGFR, and PR imaging in human breast cancer tissue specimens." (PMID 33276535, 2020). "Discovering the basis for response could lead to the effective use of EGFR-targeting therapies in a subset of breast cancer patients." (PMID 32552913, 2020). "Blockade of GPER-dependent EGFR transactivation in breast cancer cells is effective using a Gβγ-sequestrant peptide, and further study is needed to evaluate whether Gβγ-inhibitors are effective in mouse models of metabolic disorder and cancer." (PMID 33329395, 2020). "PGRMC1 may mediate proliferation and progression of breast cancer cells potentially by altering lipid metabolism and by activating key oncogenic signaling pathways, such as ERα expression and activation, as well as EGFR signaling." (PMID 32660617, 2020). "Similar to SHIP2, SYNJ2 also plays a role in regulating EGFR turnover in breast cancer cells." (PMID 33276499, 2020). "This approach has been employed to produce exosomes that express SIRPα and blockCD47-SIRPα interactions between tumor cells and T lymphocytes, and to generate exosomes expressing the EGFR-specificpeptide GE11 to promote their interaction with EGFR-positive breast cancer cells." (PMID 32257533, 2020). "Furthermore, the use of inhibitors has shown that metalloproteinases secretion and proliferation of breast cancer cells relies on EGFR transactivation and activation of the EGFR/ERK1/2 MAPK cascade." (PMID 33117280, 2020). "Taken together, these data indicated that the sustained exposure to IGFBP-1 results in increased EGFR signaling in breast cancer cells and this transition to EGF sensitivity is similar to the transition that occurs during development of tamoxifen resistance in breast cancer cells." (PMID 32435229, 2020). "In addition, transient rises in ctDNA have been observed following systemic therapy, such as immunotherapy in melanoma, neoadjuvant combined cytotoxic/biologic combination therapy in breast carcinoma and tyrosine kinase inhibition in EGFR-mutant NSCLC." (PMID 32471446, 2020).
breast carcinoma (continued). "We tested transduction of the rAAV2-based viral particles into the fibrosarcoma cell line A431, with a high copy number (approx. > 2 × 106 per cell) of EGFR on its surface and, for comparison, into the breast cancer cell line MCF7 with low expression level of EGFR." (PMID 33333826, 2020). "However, invasive melanoma cells were associated with AKT1 signaling related to the migration pathway, squamous cells with the EGFR signaling in response to extracellular cues and breast cancer cells with IL-6 signaling involved in the inflammatory response." (PMID 33142759, 2020). "MIG6/EGFR ratio could be tested as a new biomarker for predicting TKI response in breast carcinomas." (PMID 32377505, 2020). "However, investigations conducted in basal-like breast cancer, a subtype also known as Triple-Negative breast cancer, where EGFR is often overexpressed demonstrated that relationship between these phenomena are more complex than previously thought." (PMID 33302515, 2020). "In consistence, an existing study showed that overexpressing MDR1 in breast cancer cells caused no significant change in EGFR level." (PMID 32655137, 2020). "Importantly, breast cancers that over-express EGFR and exhibit increased metastatic potential, are resistant to EGFR inhibitors." (PMID 31597954, 2020). "This study also demonstrated that rhein has the potential to sensitize breast cancer cells to taxol by decreasing the levels of phospho-epidermal growth factor receptor (p-EGFR), thus unravelling the potential of this anthraquinone for the management of drug resistance in breast cancer cells." (PMID 32408623, 2020). "Indeed, Chu and colleagues showed that the use of both tamoxifen and lapatinib (an EGFR inhibitor) restored the sensitivity of breast cancer MCF-7 cells to tamoxifen." (PMID 32526980, 2020). "This was reported for a number of tumor-associated antigens such as Ep-CAM for colon carcinoma, HER2/neu for breast carcinoma, EGFR for epithelial, colorectal and renal cell carcinoma, HLA class II, CD20 and CD30 for B-cell lymphoma, and carcinoembryonic antigen as shown in in vitro studies." (PMID 32983165, 2020). "Importantly, epidermal growth factor receptor (EGFR) is more often overexpressed in TNBC than in other breast cancer subtypes, making this a possible target for therapeutic intervention." (PMID 32414394, 2020). "EGFR is a strong therapeutic target in many solid tumors including lung cancer, colorectal cancer, ovary, kidney, head and neck, prostate cancer, and especially breast cancer cells." (PMID 32977707, 2020). "Taken together, this suggests that Annexin A2 is involved in processes that promote breast cancer disease progression and this could be particularly true for tumors driven by EGFR overexpression." (PMID 32629869, 2020). "However, we are the first to show that phosphorylation of EGFR at T654 corresponds to increased breast cancer metastasis in vivo." (PMID 31597954, 2020). "Furthermore, recently, dual and pan-targeted EGFR inhibitors have also been implemented to treat breast cancer patients." (PMID 33024132, 2020). "Additionally, the injected breast cancer cells maintained their original characteristics such as sustained expression of ER (i.e. as demonstrated by positive expression of PR-B), EGFR and overexpression of aromatase." (PMID 32366373, 2020). "In addition, we are the first to show that pT654 EGFR expression increases with higher human breast cancer stages (i.e., stage 3 » stage 1 and 2 breast cancers)." (PMID 31597954, 2020). "Even though a driver mutation of the RAS signaling pathway, oncogenic K-RAS, is present in only 5% of breast cancer patients, the EGFR/HER2/K-RAS pathway is active in a large percentage of locally advanced, chemo-resistant, relapsed, and metastatic mammary tumors." (PMID 32542231, 2020). "In addition, we discovered six genes: CCNE1, CEP55, EGFR, EXO1, FGFR4, and MAPT associated with both types of breast cancer." (PMID 32724790, 2020).
breast carcinoma (continued). "One of the important molecular predictors of prognosis in breast cancer is EGFR." (PMID 33144882, 2020). "This is the case for the sensitivity to HER2-inhibitors for tumors with ERBB2 amplification in breast cancer, the vemurafenib sensitivity of BRAF-mutant cells in melanoma, or the relevance of EGFR mutation for EGFR-inhibitor treatments in non-small cell lung cancer (NSCLC)." (PMID 32645997, 2020). "Targeting UCH-L1 may increase and maintain ERα level by promoting the degradation of EGFR, thereby sensitizing ERα (-) breast cancer cells to the selective ER modulator such as tamoxifen." (PMID 32042339, 2020). "Therefore, disruption of ligand-induced EGFR dimerization as well as ligand binding would be a promising therapeutic strategy for the treatment of breast cancer patients with aberrant expression or activation of EGFR." (PMID 33050232, 2020). "Notably, established protein biomarkers for metastatic breast cancer, such as EGFR, HSPD1, PRDX6, and TPM4, which are related to lymph node and regional metastasis, were also detected." (PMID 32489334, 2020). "ERBB2 β3‐αC deletions were only found in breast cancers and sensitive to EGFR/ERBB2 inhibitor." (PMID 32757330, 2020). "Case reports have also shown that EGFR positive breast cancer might be responsive to lapatinib and capecitabine." (PMID 32613208, 2020). "Indeed, Src activation is a critical event in the signaling downstream EGFR during breast cancer progression, stimulating migration and invasion of surrounding tissues." (PMID 32498343, 2020). "Although somatic SHP2 mutations are rare in solid tumors, aberrant activation of upstream RTKs, such as the overexpression of HER2 in breast cancer and EGFR in colon cancer, has been shown to activate SHP2 to promote cancer development, progression, and resistance to targeted therapies." (PMID 31462705, 2020). "High-dose nicotine (0.5 μM) has been shown to activate the EGFR pathway in breast cancer cells, although the underlying mechanism is not elucidated." (PMID 32957649, 2020). "In breast cancer cells, this monounsaturated fatty acid promotes an increase in matrix metalloproteinase-9 secretion and invasion through a Protein kinase C, Src, and EGFR-dependent pathway." (PMID 32143529, 2020). "Having found that many of the genes inhibited by THZ1 are regulated in an EGF-dependent manner, we hypothesized that inhibition of CDK7-mediated transcription via THZ1 could potentiate the effects of EGFR inhibition in breast cancer." (PMID 32155786, 2020). "Similarly, a positive correlation was observed between staining intensity scores of resistin and EGFR in breast cancer tissues (r2 = 0.1124, P < 0.001)." (PMID 33313320, 2020). "In addition, IGFBP-3 plays a role in the DNA repair response to DNA-damaging therapy and was shown to co-translocate to the nucleus of breast cancer cells with EGFR and DNA-dependent protein kinase in response to DNA damage, to mediate this function." (PMID 32365498, 2020). "Thus, the prognostic and predictive significance of EGFR and EGFR ligands as blood-based biomarkers in early-stage breast cancer remains undetermined." (PMID 33024132, 2020). "Spearman correlation analysis revealed significantly positive correlations between positive levels of resistin expression and EGFR-positive or strongly positive expression in breast cancer tissue specimens (r = 0.250 and P < 0.001 and r = 0.166 and P = 0.001, respectively)." (PMID 33313320, 2020). "The downregulation of ERβ prevents breast cancer cell migration through tyrosine kinase receptor [epidermal growth factor receptor (EGFR)/insulin-like growth factor-I receptor (IGF-IR)] and Janus kinase/signal transducer and activator of transcription (JAK/STAT) signaling pathways." (PMID 32944243, 2020).
breast carcinoma (continued). "Spearman correlation analysis revealed significantly positive correlations between strongly positive levels of resistin expression and EGFR-positive or strongly positive expression in breast cancer tissue specimens (r = 0.318 and P < 0.001 and r = 0.207 and P < 0.001, respectively)." (PMID 33313320, 2020). "The GRB2 is overexpressed in breast cancers, and is a key molecule in intracellular signal transduction, which can directly interact with RTKs, such as epidermal growth factor receptor (EGFR) to activate several downstream oncogenic signaling pathways, including PI3K-Akt and RAS signaling." (PMID 32350346, 2020). "GO enrichment analysis indicated that inhibition of protein tyrosine kinases autophosphorylation might be the primary mechanism for the anti-breast cancer effect of the triterpenoids, and ErbB4 and EGFR were the most relevant targets." (PMID 33246450, 2020). "Cell mortality, following the coincubation with all the three types of nanostructures and RF stimulation, was increased only in human pancreatic carcinoma cells, that overexpress EGFR, while was less relevant in human breast carcinoma cell line expressing a lower amount of EGFR." (PMID 34138198, 2020). "Considering these associations, these patients would less likely respond to HT but more likely benefit from anti-HER2 therapy as well as dual-kinase inhibitors (such as lapatinib), which target both EGFR and erb-B2 and are promising in HER2- and EGFR-expressing breast carcinomas." (PMID 32364614, 2020). "Activation of the CaSR in breast cancer cells have also been shown to stimulate cell proliferation acting through membrane metalloproteinases, upregulating the transient receptor potential channel 1, stimulating EGFR, and ERK1/2 phosphorylation." (PMID 32117726, 2020). "However, FABP5 has been reported to enhance EMT, metastatic potential and tumorigenesis through activation of the EGFR signaling pathway in breast cancer and induce EMT in hepatocellular cancer." (PMID 33352874, 2020). "Similar results were obtained for the basal EGFR+ breast cancer cell line HCC1937." (PMID 32350443, 2020). "We thus posit that PGRMC1 overexpression in breast cancer cells could promote cell survival by interacting with EGFR in the cell membrane." (PMID 32704174, 2020). "A subgroup of breast cancer patients with ER-positive tumors and markedly elevated S-EGFR levels might be of particular interest as potential candidates for EGFR-targeted treatment." (PMID 32317675, 2020). "The epidermal growth factor receptor HER2 is overexpressed in 20% of breast cancer cases." (PMID 33260837, 2020). "However, in addition to enhancing tumor phagocytosis, blocking CD47 also improves the antigen presentation by DCs and inhibits the aggressive phenotype of breast cancer stem cells (BCSCs) via inhibition of EGFR signaling." (PMID 32929084, 2020). "In addition to MITF, other amplified and overexpressed genes are HER2 in 15%–20% of invasive breast carcinomas, MYC in 15-20% of breast cancer and several hematological malignancies, EGFR in squamous cell carcinomas, MDM2 in several cancer type." (PMID 31217906, 2019). "Recent reports show resistance to receptor tyrosine kinase (RTK) inhibitors is correlated to EGFR lipid raft localization in breast cancer cells, and that disrupting lipid rafts by cholesterol depletion sensitizes these resistant breast cancer cells to EGFR inhibitors, dampening Akt activation." (PMID 31069012, 2019). "Breast cancer cells that overexpress EGFR or HER2 are sensitive to DDAs2,4,16." (PMID 31839995, 2019). "The GPER-mediated CAF-dependent estrogenic effects in the tumor-associated stroma are more likely to contribute to breast cancer progression, especially in the tamoxifen resistance, via a positive feedback loop involving the GPER/EGFR/ERK signaling pathway and E2 production." (PMID 30646517, 2019).